ARHGAP39 (Rho GTPase activating protein 39)
Synonyms: KIAA1688; Vilse; CrGAP
Tractability: PROTAC: ubiquitination databases record sites on it; its protein half-life has been measured.
Gene: Protein-coding gene on chromosome 8 (144,529,179 to 144,685,879, reverse strand). Ensembl gene ENSG00000147799.
Subcellular location: Nucleus
Subcellular location (Human Protein Atlas): Nucleoplasm
Pathways (Reactome):
Signal Transduction: CDC42 GTPase cycle; RAC1 GTPase cycle; RAC2 GTPase cycle; RAC3 GTPase cycle; RHOA GTPase cycle; RHOB GTPase cycle; RHOC GTPase cycle; RHOD GTPase cycle; RHOF GTPase cycle; RHOG GTPase cycle
Developmental Biology: Inactivation of CDC42 and RAC1
Gene Ontology:
Molecular function: GTPase activator activity
Biological process: postsynapse organization; regulation of small GTPase mediated signal transduction; signal transduction
Cellular component: glutamatergic synapse; cytoplasm; cytosol; cytoskeleton; nucleus
Genetic constraint (gnomAD): Loss-of-function variants: 44 observed, 86.03 expected, observed/expected ratio (o/e) 0.51, 90% interval 0.4 to 0.66. The synonymous counts are far from expectation, so gnomAD's model fits this gene poorly and the ratio says little. Missense variants: 1,496 observed, 1,462.4 expected, observed/expected ratio (o/e) 1.02, 90% interval 0.98 to 1.07. Synonymous variants: 768 observed, 630.79 expected, observed/expected ratio (o/e) 1.22, 90% interval 1.15 to 1.29.
Homologues: Orthologues: chimpanzee ARHGAP39 (99% identical), macaque ARHGAP39 (99% identical), guinea pig ARHGAP39 (90% identical), rat Arhgap39 (89% identical), mouse Arhgap39 (89% identical), pig ARHGAP39 (89% identical), dog ARHGAP39 (86% identical), rabbit ARHGAP39 (76% identical), tropical clawed frog arhgap39 (67% identical), zebrafish arhgap39 (59% identical), Drosophila melanogaster RhoGAP93B (35% identical), Caenorhabditis elegans Y92H12BM.1 (8% identical), and 1 more.
Diseases named in the same sentence as ARHGAP39 in open-access papers:
ARHGAP39 is named in the same sentence as 20 diseases in open-access papers, as found by Europe PMC text mining. Sharing a sentence is not in itself a finding about the gene and the disease. The quoted sentences say what the papers report.
breast carcinoma (2 papers, 2023 to 2025). "Taken together, ARHGAP39 was identified as an upregulated biomarker which was significantly associated with advanced clinicopathological factors in breast cancer." (PMID 37189064, 2023). "Our findings provide insight into the fundamental role of ARHGAP39 in breast cancer and propose underlying mechanisms of ARHGAP39 in immune infiltrates." (PMID 37189064, 2023). "Our study sheds light on understanding the underlying mechanisms of ARHGAP39 in tumor immunology and represents the diagnostic and therapeutic target for tailored therapy in breast cancer." (PMID 37189064, 2023). "ARHGAP39 was overexpressed in breast cancer and associated with poor survival outcomes." (PMID 37189064, 2023). "The expression and prognosis analysis indicated the oncogenic role of ARHGAP39 in breast cancer, and we determined its biological function in carcinogenesis." (PMID 37189064, 2023). "According to analysis of CPTAC database, higher ARHGAP39 protein expression was found in breast cancer tissues than that in normal tissues." (PMID 37189064, 2023). "ARHGAP39 was particularly upregulated in breast cancer tissues (n = 8) compared with adjacent normal tissues by qRT-PCR analysis (p = 0.0011)." (PMID 37189064, 2023). "Our findings suggested that ARHGAP39 can be used as a potential therapeutic target and prognostic biomarker in breast cancer." (PMID 37189064, 2023). "Consistently, ARHGAP39 protein expression was upregulated in breast cancer samples compared with normal samples." (PMID 37189064, 2023). "Analysis of transcriptomes of breast cancer in TCGA database demonstrated higher ARHGAP39 expression in tumor tissues than normal tissues, and our qRT-PCR results reached a consistent conclusion." (PMID 37189064, 2023). "ARHGAP39 expression in patients with luminal breast cancer was higher than that in HER2-positive breast cancer (p < 0.05)." (PMID 37189064, 2023). "Because of transcriptomic and proteomic analysis of above molecules, we focused on the biological functions ARHGAP39 on the development of breast cancer." (PMID 37189064, 2023). "We conducted GSEA analysis to identify important pathways to characterize the potential biological mechanisms of ARHGAP39 in breast cancer." (PMID 37189064, 2023). "We confirmed that ARHGAP39 was upregulated in breast cancer and its expression level was correlated with poor prognosis and advanced clinical characteristics." (PMID 37189064, 2023). "We analyzed mRNA and protein expression of ARHGAP39 in human breast cancer based on TCGA and CPTAC databases." (PMID 37189064, 2023). "We conducted in vitro experiments including cell viability assays and transwell assays to confirm the biological function of ARHGAP39, and the results confirmed that ARHGAP39 could foster breast cancer cell proliferation, migration, and invasion." (PMID 37189064, 2023). "Collectively, ARHGAP39 might influence immune infiltration, and the role of ARHGAP39 in tumor immunology of breast cancer should be comprehensively analyzed." (PMID 37189064, 2023). "In vitro experiments revealed that ARHGAP39 could facilitate the proliferation, migration, and invasion capability of breast cancer cells." (PMID 37189064, 2023). "At present, we found an essential role of ARHGAP39 in breast cancer immunity." (PMID 37189064, 2023). "First, we estimated the expression level and prognostic value of ARHGAP39 in breast cancer." (PMID 37189064, 2023). "Altogether, ARHGAP39 was upregulated in breast cancer and could be a treatment predictive biomarker during clinical decisions." (PMID 37189064, 2023). "In conclusion, our study provided a comprehensive profiling of ARHGAP39 in breast cancer which could strengthen our understanding of the molecular mechanisms of breast cancer and aid in biomarker discovery." (PMID 37189064, 2023).
breast carcinoma (continued). "The existing research results of the co-expressed gene could partially explain that ARHGAP39 as a prognostic biomarker influence immune infiltration in breast cancer." (PMID 37189064, 2023). "These correlations could be indicative of a potential mechanism where ARHGAP39 regulates T cell functions and macrophage functions in breast cancer." (PMID 37189064, 2023). "Together, we confirmed that ARHGAP39 could promote the proliferation, migration, and invasion of breast cancer." (PMID 37189064, 2023). "Moreover, we explored the impact of ARHGAP39 in regulating immune infiltration of breast cancer." (PMID 37189064, 2023). "However, there are few studies on the comprehensive analysis of ARHGAP39 in breast cancer." (PMID 37189064, 2023). "Furthermore, ARHGAP39 potentially regulated the immune-related pathways, and affected the tumor-infiltrating immune cells, thus providing opportunities for the development of novel immunotherapies for breast cancer treatment." (PMID 37189064, 2023). "Under the condition of relative expression level, we knocked down ARHGAP39 by introducing two independent specific siRNAs in MDA-MB-231 and CAL51 breast cancer cells, followed by qRT-PCR analysis." (PMID 37189064, 2023). "However, there is still a lack of evidence for the role of ARHGAP39 in breast cancer." (PMID 37189064, 2023).
gastric cancer (2 papers, 2021 to 2023). A primary or metastatic malignant neoplasm involving the stomach. "Rho GTPase activating protein 39 (ARHGAP39) is a crucial activating protein of Rho GTPases, a novel target in cancer therapy, and it was identified as a hub gene for gastric cancer." (PMID 37059586, 2023).
hepatocellular carcinoma (2 papers, 2023 to 2025). A malignant tumor that arises from hepatocytes. "Studies have shown that ARHGAP39 is highly expressed in hepatocellular carcinoma and relevant to clinicopathological features." (PMID 37059586, 2023). "In brief, ARHGAP39 is a promising prognostic factor for hepatocellular carcinoma patients that is closely related to cell cycle, immune infiltration, m6A modification, and drug resistance." (PMID 37059586, 2023). "Accordingly, the cancer genome atlas (TCGA) data were used to analyze the expression and clinical value of ARHGAP39 in hepatocellular carcinoma." (PMID 37059586, 2023). "We first noticed that several online websites showed that ARHGAP39 was abnormally highly expressed in hepatocellular carcinoma tissues, which was the same as the analysis conclusions of the TCGA and ICGC databases." (PMID 37059586, 2023). "Since the aberrations of MEK/ERK signaling substrates play important roles in developing HCC, Arhgap39 might be a novel modulator in several hepatocellular carcinoma cells." (PMID 39866228, 2025). "In conclusion, these results indicate that ARHGAP39 may promote the tumorigenesis and progression of hepatocellular carcinoma by participating in cell cycle and metabolism related pathways." (PMID 37059586, 2023). "Arhgap39 loss could modulate the migration and invasion in some hepatocellular cancer cells, but not in those isolated from KPA mice." (PMID 39866228, 2025). "Notably, ARHGAP39 may worsen the survival of hepatocellular carcinoma patients by increasing the level of immune infiltration through chemokines." (PMID 37059586, 2023). "However, the expression and role of ARHGAP39 in hepatocellular carcinoma remain unclear." (PMID 37059586, 2023).
mastitis (2 papers, 2015 to 2020). Inflammation of breast tissue during lactation or postpartum due to an obstructed duct or infection. "Comparison with indigenous pigs showed genes that were associated with mastitis resistance (ARHGAP39, ARPC4, PHC2, and BCL2L15) and hair follicle development (FOXN1)." (PMID 32457791, 2020). "TRAPPC9 and ARHGAP39 genes reveal the two novel candidate genes associated with mastitis resistant traits in dairy cattle." (PMID 26370837, 2015). "Two genes (TRAPPC9 and ARHGAP39) identified by significant SNPs indicate that they are important candidate genes associated with mastitis-related traits." (PMID 26370837, 2015). "TRAPPC9 and ARHGAP39 genes (each contains three significant SNPs on genome level) identified by MMRA can be considered potential candidate genes for mastitis-related traits." (PMID 26370837, 2015).
Anxiety (1 paper, 2026). Intense feelings of nervousness, tension, or panic often arise in response to interpersonal stresses. "In conclusion, our findings demonstrate that ARHGAP39 plays a critical role in modulating anxiety, hippocampal neurogenesis, and synaptic stability, highlighting it as a promising target for developing anxiolytic therapies." (PMID 42106334, 2026). "In this study, we identified a strong link between ARHGAP39 function and anxiety using brain-specific Arhgap39 conditional knockout (cKO) mice." (PMID 42106334, 2026). "Finally, hippocampal overexpression of Arhgap39 in C57BL/6 mice did not affect baseline behavior but alleviated chronic stress-induced anxiety in light-dark box test." (PMID 42106334, 2026).
autism (1 paper, 2025). Persistent deficits in social interaction and communication and interaction as well as a markedly restricted repertoire of activity and interest as well as repetitive patterns of behavior. "In addition, genes involved in learning and memory (ARHGAP39 and HERC1), intellectual disability (SOBP), or autism (NF1), whose mutations cause neurodevelopmental, behavioral, learning, and motor abnormalities, are repressed by exercise and normalized or slightly induced upon subsequent rest." (PMID 40725218, 2025).
diabetes (1 paper, 2018). "Thus the decrease in Arhgap39/Porf-2 could be a result of increased suppression by insulin in the prediabetic state, although later, as insulin resistance with hyperinsulinemia advances to frank diabetes, Arhgap39/Porf-2 levels can be anticipated to rise." (PMID 30406180, 2018).
glioblastoma (1 paper, 2023). The most malignant astrocytic tumor (WHO grade IV). "ARHGAP39 was significantly decreased in 7 cancers: glioblastoma multiforme (GBM), pan-kidney cohort (KIPAN), kidney renal clear cell carcinoma (KIRC), thyroid carcinoma (THCA), testicular germ cell tumors (TGCT), adrenocortical carcinoma (ACC), and kidney chromophobe (KICH)." (PMID 37189064, 2023).
Insulin resistance (1 paper, 2018). Increased resistance towards insulin, that is, diminished effectiveness of insulin in reducing blood glucose levels. "Two recent findings suggest a link between insulin resistance and Arhgap39/Porf-2." (PMID 30406180, 2018).
liver cancer (1 paper, 2025). An epithelial or non-epithelial malignant neoplasm that arises from the liver. "Our study suggests a potential carcinogenic effect of Arhgap39 in liver cancer progression, especially in Hepa1-6 and Hepa-1c1c7 cells." (PMID 39866228, 2025). "However, Arhgap39 still modulates the invasive potentials in aberrant Hepa1-6 and Hepa-1c1c7 liver cancer cells." (PMID 39866228, 2025).
renal clear cell carcinoma (1 paper, 2025). "An elevated Arhgap39 expression is associated with low survival in human patients suffering from liver hepatocellular carcinomas and renal clear cell carcinoma." (PMID 39866228, 2025).
tumor (6 papers, 2018 to 2026). "ARHGAP39 expression was positively associated with tumor stages and the mRNA expression in stage 3 was significantly higher than in stage 1 and stage 2 (p < 0.01)." (PMID 37189064, 2023). "ARHGAP39 mutations or variations in copy number or expression level were found in several types of tumor-like tissues from the central nervous system, skin, prostate, and gastrointestinal tract." (PMID 33717664, 2021). "We analyzed the differences in ARHGAP39 mRNA expression between tumor and its adjacent normal tissues in pan-cancer using the TCGA and GTEx datasets." (PMID 37189064, 2023). "Among our research, our group studied the function of ARHGAP39 in HCC from the expression level of ARHGAP39, survival analysis, the relationship between ARHGAP39 and cell cycle, tumor-infiltrating immune cells, m6A modification, drug sensitivity, and so on." (PMID 37059586, 2023). "ARHGAP39 expression level was analyzed based on the Cancer Genome Atlas (TCGA), the Genotype-Tissue Expression Project (GTEx), and the Clinical Proteomic Tumor Analysis Consortium (CPTAC) database and validated by qPCR in various cell lines and tumor tissues." (PMID 37189064, 2023). "We measured the levels of ARHGAP39 expression in different cohorts based on age, gender, tumor grade and stage, and T and N classification to validate the link between ARHGAP39 and multiple clinic pathological features." (PMID 37059586, 2023). "Additionally, the differential expression level of ARHGAP39 was explored in biological subtypes, tumor grade, ER status, PR status, and HER2 status." (PMID 37189064, 2023). "The correlations between ARHGAP39 and cancer immune infiltrates were investigated via TIMER, CIBERSORT, ESTIMATE and tumor-immune system interactions database (TISIDB)." (PMID 37189064, 2023). "One plausible explanation is that Arhgap39 is not a critical initiator or driver for tumor progression." (PMID 39866228, 2025). "The ESTIMATE algorithm was used to predict tumor purity, the expression of ARHGAP39 showed significant negative correlation with immune score, stromal score, and ESTIMATE score." (PMID 37189064, 2023).
cancer (4 papers, 2015 to 2025). A tumor composed of atypical neoplastic, often pleomorphic cells that invade other tissues. "As a result, studying the expression and related mechanisms of ARHGAP39 in cancers is likely to be extremely beneficial to cancer treatment." (PMID 37059586, 2023). "The results verified that ARHGAP39 was increased in cancer cells in comparison with MCF10A epithelial cell control." (PMID 37189064, 2023). "Next, we studied mRNA expression level of ARHGAP39 in different molecular subtypes, cancer stages, and ages." (PMID 37189064, 2023). "As for ARHGAP39 gene, it was proved to be function to activate Rho GTPase which is known as new targets in cancer therapy." (PMID 26370837, 2015). "Therefore, the GeneMANIA database was utilized to build an interaction network between ARHGAP39 and other cancer-related proteins." (PMID 37059586, 2023). "The high expression of ARHGAP39 mRNA was detected in 13 types of cancer, including LIHC." (PMID 37059586, 2023). "ARHGAP39 protein expression was correlated with cancer stage and patients’ age." (PMID 37189064, 2023). "Immunoblotting results showed that Arhgap39 was genuinely absent in KPAΔ/Δ cancer cells." (PMID 39866228, 2025). "First of all, we assessed the correlation between promoter methylation and ARHGAP39 expression in HCC tissues and para-carcinoma tissues via the UALCAN web resource, which indicated that promoter methylation is more common in carcinoma tissues than in para-carcinoma tissues." (PMID 37059586, 2023).
ARHGAP39 also shares sentences with these, for which no sentence is quoted: Ewing sarcoma (1 paper); fibromatosis (1); Hyperinsulinemia (1); Intellectual disability (1); kidney chromophobe (1); testicular germ cell tumor (1); thyroid carcinoma (1).